IFITM3 (interferon induced transmembrane protein 3)
Diseases named in the same sentence as IFITM3 in open-access papers (continued):
Sharing a sentence is not in itself a finding about the gene and the disease.
colon cancer (16 papers, 2015 to 2024). "IFITM3 is a poor prognostic factor in colonic cancer and an independent risk factor for disease-free interval." (PMID 33364194, 2020). "The first evidence for the cancer association of Wnt and IFITM3 comes from colonic cancer." (PMID 33364194, 2020). "Aberrant KLF4 is associated with overexpression of IFITM3 in colon cancer." (PMID 33364194, 2020). "We further inoculated WT and KO mice with MC38 murine colon cancer cells subcutaneously to determine the function of IFITM3 in vivo." (PMID 38167862, 2024). "Early research revealed that IFITM3 is a tumor biomarker, followed by its observed upregulation in colon cancer." (PMID 34456915, 2021). "The role of IFITM3 in cancer needs reassessing, as recent evidence suggests IFITM3 is one of the first genes activated in mouse colon cancer models and precancerous colonic adenomas." (PMID 33364194, 2020). "The data obtainedfrom this study suggest that IFITM3 plays an importantrole in early colon cancer development." (PMID 30983867, 2018). "Conversely, knock-down of IFITM3 expression in colon cancer cells by a specific siRNA significantly suppressed proliferation, colony formation, migration, and invasion in vitro as well as tumor growth and metastasis in a xenograft model." (PMID 27835870, 2016). "IFITM3 has been reported to be upregulated in colon cancer patients as well as in inflamed colon mucosa and was proposed as a diagnostic marker in colorectal tumors." (PMID 27835870, 2016). "To address this hypothesis, we inoculated WT and cKO mice with MC38 murine colon cancer cells subcutaneously to determine whether Ifitm3 is required for Treg cells in anti-tumor responses in vivo." (PMID 38167862, 2024). "Downregulate IFITM3 expression level could significantly restrain the proliferation, migration, and invasion in colon cancer cells and also inhibit tumor growth and metastasis in animal models." (PMID 31273201, 2019). "In addition, the interferon-responsive gene Ifitm3 is critical to early colon cancer development, along with S100a9 and Slpi, which, when highly expressed in inflamed colon tissues in mice and patients with colitis and IBD, respectively, can be considered as potent amplifiers of tumor invasion." (PMID 36901742, 2023). "We crossed IFNγ+/− mice with IFITM3 cKO mice (to generate IFNγ+/− cKO mice) and inoculated them with MC38 murine colon cancer cells." (PMID 38167862, 2024). "For instance, in colon cancer, KLF4 inversely modulates IFITM3, and the dysregulation of KLF4 expression results in IFITM3 abnormal expression, which is the cause of progression and metastasis of cancer cells." (PMID 35027543, 2022). "Additionally, PCIF1 has been reported to regulate colon cancer growth and response to anti-PD-1 by stabilizing cancer-promoting gene mRNAs, such as FOS, IFITM3, and STAT1, through m6Am modifications." (PMID 39451207, 2024). "In a study in colorectal cancer, IFITM3 was expressed at higher levels in tumors, especially in nodal metastases, than in normal colon tissue, and the silencing of IFITM3 suppressed tumor growth and metastasis in a xenograft model of HCT116 colon cancer cells." (PMID 32668617, 2020). "In colon cancer, adaptor related protein complex 1 subunit mu 1 (AP1M1), subunit sigma 2 (AP1S2), and subunit sigma 3 (AP1S3) are common overregulated genes and might be related to the accumulation of IFITM3 protein on the cell surface." (PMID 39228892, 2024).
HIV-1 infection (16 papers, 2014 to 2025). The type species of lentivirus and the etiologic agent of acquired immunodeficiency syndrome (AIDS). "Our findings presented here, in the context of HIV-1 infection, corroborate those data in that primate isolates of Nef counteracted IFITM3 antiviral function in a manner associated with its downmodulation from the cell surface." (PMID 40463006, 2025). "Our findings presented here, in the context of HIV-1 infection, corroborate those data in that primary isolates of Nef counteracted IFITM3 antiviral function in a manner associated with its downmodulation from the cell surface." (PMID 41032588, 2025). "Together, these findings indicate that megakaryocyte precursors are susceptible to HIV-1 infection, leading to terminally differentiated megakaryocytes harboring virus in a process regulated by IFITM3." (PMID 39354676, 2025). "One implication of this finding is that relatively high level of IFITM3 may mount high enough inhibitory pressure to limit Env mutation pathways in evading inhibition by antibodies, thus creating a synergistic control of HIV-1 infection." (PMID 30935048, 2019). "Furthermore, it will be interesting to examine the effect of the IFITM3 SNP rs12252 on HIV-1 infection: would aberrant localization of IFITM3 at the plasma membrane make HIV-1 more or less susceptible to restriction?" (PMID 25422110, 2014). "IFITM3 knockdown in MEG-01 cells prior to infection led to enhanced HIV-1 infection, indicating that IFITM3 acts as an HIV-1 restriction factor in megakaryocytes." (PMID 39354676, 2025). "Here we report that restriction of HIV-1 infectivity following ectopic IFITM3 expression in virus-producing cells (epithelial cells or T lymphocytes) is counteracted by Nef proteins obtained from primary isolates of acute HIV-1 infection." (PMID 40463006, 2025). "To demonstrate the direct role of IFITM3 in mature megakaryocyte infection, we knocked down its expression in the megakaryocytic MEG-01 cell line with an IFITM3-specific small interfering RNA (siRNA) prior to HIV-1 infection." (PMID 39354676, 2025). "In this study we found that the HIV-1 infection of cord blood CD34+ cell-derived megakaryocyte precursors inhibits IFITM3 expression on Day 7 post-infection when megakaryocytes are terminally differentiated in vitro." (PMID 39354676, 2025). "On the other hand, when assessing the effect of IFITM3 on infection, we found that silencing IFITM3 enhanced HIV-1 infection, indicating that HIV counteracts the intrinsic antiviral response of megakaryocytes mediated by IFITM3." (PMID 39354676, 2025). "We found that the HIV-1 infection of megakaryocyte precursors resulted in the generation of terminally differentiated infected megakaryocytes with diminished IFITM3 expression." (PMID 39354676, 2025). "The HIV-1 infection of megakaryocytes in their progenitor state alters the expression of genes involved in viral response, including IFITM3, allowing for the virus to persist in these cells." (PMID 39354676, 2025). "The Vpr-TET2 axis enhances HIV-1 infection in MDMs by reducing IFITM3 expression via a TET2 dioxygenase-dependent mechanism and by sustaining IL-6 induction via TET2 dioxygenase-independent mechanisms." (PMID 31431548, 2019). "The Vpr-TET2 axis enhances HIV-1 replication in MDMs by reducing IFITM3 expression and by sustaining IL-6 induction after HIV-1 infection." (PMID 31431548, 2019). "Immune-related IFITM proteins have been established as important antiviral effectors of the interferon response, and a polymorphism in the human IFITM3 gene has been found to be associated with disease severity and progression in FLUAV and HIV-1 infection." (PMID 28257482, 2017). "The HIV-1 infection augmented by three times the macrophage IFITM3 levels (as detected 14 days after infection), relative to IFITM3 contents in uninfected cells." (PMID 24978204, 2014).
HIV-1 infection (continued). "Although this is the first time, to our knowledge, that IFITM3 downregulation has been demonstrated in HIV-1 infection, Chikungunya virus and Mayaro virus have been reported to induce IFITM3 downregulation in infected cells." (PMID 39354676, 2025). "It will be important to assess whether counteraction of IFITM3 is also a feature of Nef proteins isolated during chronic stages of HIV-1 infection." (PMID 40463006, 2025). "Our findings may suggest that counteraction of IFITM3 by Nef is important during early stages of HIV-1 infection in vivo." (PMID 40463006, 2025). "Because we found that primary isolates of Nef obtained from acute clade C, clade D, and clade F HIV-1 infection were capable of counteracting HIV-1 restriction by IFITM3, we next examined Nef proteins from clade B HIV-1, which is the predominant form of HIV-1 in North America." (PMID 41032588, 2025). "Since we found that primary isolates of Nef obtained from acute clade C, clade D, and clade F HIV-1 infection were capable of counteracting HIV-1 restriction by IFITM3, we next examined Nef proteins from clade B HIV-1, which is the predominant form of HIV-1 in North America." (PMID 40463006, 2025). "Together, these recent data suggest that IFITM2 and IFITM3 may be major selective pressures responsible for the use of CCR5 during primary HIV-1 infection." (PMID 29162141, 2017). "We subsequently evaluated whether HIV-1 infection also enhances IFITM3 in human primary macrophages." (PMID 24978204, 2014). "HIV-1 infection also increased IFITM3 levels in human primary macrophages by almost 100%." (PMID 24978204, 2014). "In addition, following HIV-1 infection of megakaryocyte precursors, the expression of interferon-induced transmembrane protein 3 (IFITM3), an antiviral factor constitutively expressed in megakaryocytes, was inhibited in terminally differentiated HIV-1-infected megakaryocytes." (PMID 39354676, 2025). "However, in contrast to acute in vitro DENV infection, in this study, we found that the HIV-1 infection of megakaryocyte precursors at Day 0 post-infection inhibits IFITM3 expression later on at Day 7 post-infection when megakaryocytes are terminally differentiated." (PMID 39354676, 2025). "On the other hand, HIV-1 infection triggers the over-expression of several RFs genes, including IFITM1, IFITM2, IFITM3, MX1, MX2, TETHERIN, IFN1a, and IFNR." (PMID 39476027, 2024). "They found that persistent HIV-1 infection in humanized-mice led to induction of IFNs and ISGs including MX2, IFITM3, Trim22, ISG15, OAS1, and IFN regulatory factor 7 (IRF7) both in peripheral blood mononuclear cells (PBMCs) and in the spleen." (PMID 30665429, 2019). "We further analyzed spreading HIV-1 infection of Vpr+ and Vpr− HIV-1 in MDMs for 6 days with depletion of TET2 or IFITM3 treated with IL-6 neutralizing antibody." (PMID 31431548, 2019). "IFITM3 restricts HIV-1 infections at different stages of the HIV-1 replicative cycle by blocking viral entry through IFITM3 incorporation on virions and direct interactions between IFITM3 and HIV-1 env, and at later stages of infection when IFITM3 blocks viral protein synthesis." (PMID 39354676, 2025). "Thus, Nef from primary HIV-1 isolates can antagonize human IFITM3, and this is particularly evident for Nef originating from acute clade C, which is the most prevalent form of HIV-1 and accounts for ~50% of HIV-1 infections globally." (PMID 41032588, 2025). "We evaluated IFITM3 protein expression in mature megakaryocytes in the presence or absence of HIV-1 infection." (PMID 39354676, 2025). "Thus, Nef from primary HIV-1 isolates can antagonize human IFITM3, and this is particularly evident for Nef originating from acute clade C, which is the most prevalent form of HIV-1 and accounts for approximately 50% of HIV-1 infections globally." (PMID 40463006, 2025).
HIV-1 infection (continued). "As we observed IFITM3 downregulation in the later stages of HIV-1 infection and not during the acute phase, it is therefore reasonable to speculate that the viral mechanisms controlling IFITM3 expression may differ." (PMID 39354676, 2025). "Indeed, we have observed that FLAG-tagged IFITMs are approximately 25–30% more potent than their WTs to inhibit HIV-1 infection; however, the order of potency in inhibition for the untagged WT IFITMs and FLAG-IFITMs remains the same, that is, IFITM3 > IFITM2 > IFITM1." (PMID 30087232, 2018). "However, an association between rs12252-C and more rapid progression to AIDS, but not risk of HIV-1 infection, has been demonstrated, and the reason for the discrepancy between these results and the increased anti-HIV-1 activity of truncated IFITM3 in cell culture is at present unclear." (PMID 28257482, 2017). "During HIV-1 infection of macrophages, in the absence of Vpr, TET2 demethylates the IFITM3 promoter, relieving suppression, contributing to the antiviral response." (PMID 38951492, 2024). "The results showed that mRNA levels of already known host restriction factors which inhibit HIV-1 infection, TRIM5α, MX2, SAMHD1, SERINC3, SERINC5, IFITM2, IFITM3, ApoE, and PSGL-1 were not significantly elevated by γ-IFN." (PMID 35883685, 2022).
hepatocellular carcinoma (15 papers, 2020 to 2025). A malignant tumor that arises from hepatocytes. "Previous studies have linked elevated IFITM3 expression to tumor progression in glioblastoma, gastric, and hepatocellular carcinomas, where it regulates key pathways, such as cell proliferation, angiogenesis, and epithelial-mesenchymal transition (EMT)." (PMID 40611157, 2025). "The obtained results of this study indicated, the codominant model of CC genotype of IFITM3 gene had high association with risk of hepatocellular carcinoma with odd ratio (OR) 2.70 with significant p = 0.041." (PMID 37353775, 2023). "For IFITM3 rs 12252-CC gene polymorphisms, the results in this study showed that the homozygous TT genotypic frequency in hepatocellular carcinoma patients (11%) that was less than which founded in control group (23%)." (PMID 37353775, 2023). "The study suggested that the CC genotype of IFITM3 rs 12252-CC polymorphisms might be associated with the risk of hepatocellular carcinoma and screening genotypes of IFITM3 for diagnosis and starting intervention of the disease is necessary." (PMID 37353775, 2023). "In late endosomes exists IFITM3, there are numerous IFITM3 single nucleotide polymorphisms (SNPs) in the translated sequence of IFITM3, and the rs12552 CC genotype has been correlated to hepatocellular carcinoma with poor differentiation, high development, and a greater relapse rate." (PMID 37353775, 2023). "For the dominant model (CT + CC) of IFITM3 gene, the results showed that there is statistically high association with risk of hepatocellular carcinoma with odd ratio 3.02 and significant p = 0.01, the CC recessive model odd ratio = 2.70 and high association with risk of hepatocellular carcinoma." (PMID 37353775, 2023). "Results revealed that IFITM3 rs 12252-CC among Hepatocellular carcinoma patients would allow diagnosis and starting intervention." (PMID 37353775, 2023). "The obtained results of this study indicated that IFITM3 rs 12252-CC was significantly elevated in HCC group, the codominant model of CC genotype of IFITM3 gene had high association with risk of hepatocellular carcinoma with odd ratio (OR) = 2.70, p = 0.041." (PMID 37353775, 2023). "IFITM3 promotes hepatocellular carcinoma invasion and metastasis by regulating MMP9 through p38/MAPK signaling." (PMID 38149381, 2023). "The study aimed to investigate the over expression of IFITM3 in hepatocellular carcinoma Egyptian patients." (PMID 37353775, 2023). "Next, the PPI between NTCP and IFITM3 was analyzed in two human hepatoma cell lines, namely HepG2 and HuH7, which were stably transfected with an NTCP-FLAG construct." (PMID 35458456, 2022). "IFITM3 is increasingly reported as a oncogene in various cancer types such as hepatocellular carcinoma (HCC), glioma, B cell malignancies, colon, prostate, breast and gastric cancers." (PMID 35941699, 2022). "The present study investigated the role of TUG1 and its downstream genes miR-29a and IFITM3 in the occurrence and development of hepatocellular carcinoma (HCC)." (PMID 34659578, 2021). "IFITM3 also promoted metastasis in xenograft models of hepatocellular carcinoma and prostate cancer." (PMID 32668617, 2020). "A close association between IFITM3 and c-myc is observed in B-cell acute lymphoblastic leukemia (B-ALL) and hepatocellular cancer cell lines." (PMID 33364194, 2020). "IFITM3 play an important role in progression of hepatocellular carcinoma." (PMID 37353775, 2023). "Interferon-induced transmembrane protein 3 (IFITM3) is a key signaling molecule regulating cell growth in some tumors, but its function and mechanism in hepatocellular carcinoma (HCC) remain unknown." (PMID 33816616, 2021). "MicroRNA miR-29a suppresses the growth and metastasis of hepatocellular carcinoma (HCC) through IFITM3, and knockdown of IFITM3 promoted apoptosis of HCC cells." (PMID 40681213, 2025).
hepatocellular carcinoma (continued). "once testified IFITM3’s promotion influences on hepatocellular carcinoma (HCC) invasion and metastasis by regulating MMP9 through p38/MAPK signaling." (PMID 37304304, 2023). "In conclusion, IFITM3 was identified as a novel NTCP co-factor that significantly affects in vitro infection with HBV and HDV in NTCP-expressing hepatoma cells and PHHs." (PMID 35458456, 2022). "IFITM3 was identified as a novel co-factor of NTCP that significantly affects in vitro infection with HBV and HDV in NTCP-expressing hepatoma cells and PHHs." (PMID 35458456, 2022). "After the immunoprecipitation of NTCP, Western blot analysis with the IFITM3 antibody revealed co-precipitation of IFITM3, clearly confirming the PPI of NTCP and IFITM3 also in hepatoma cells." (PMID 35458456, 2022). "IFITM3 enhanced the invasion and metastasis of hepatocellular carcinoma through regulating expression of MMP9 via the p38/MAPK pathway and promoted proliferation of hepatocellular carcinoma via regulating expression of c-myc through the ERK1/2 signaling pathway." (PMID 33384961, 2020). "Additionally, IFITM3 is a negative prognostic marker in treatment outcome in esophageal and hepatocellular cancer, but, interestingly, not in glioblastomas." (PMID 33364194, 2020).